LAG3 (lymphocyte activating 3)
Diseases named in the same sentence as LAG3 in open-access papers (continued):
Sharing a sentence is not in itself a finding about the gene and the disease.
tumor (continued). "Some of these clinical trials have indicated promising results, in which the combination of anti-PD-1 and anti-LAG-3 blockade has a synergistic anti-tumor effect compared with monotherapy, and could improve the efficacy in patients who are resistant to anti-PD-1 therapy." (PMID 32714324, 2020). "On the other hand, the co-expression of MHC class II on tumor cells and LAG-3 on CD8 REP-TILs is a potential limitation for the anti-tumor reactivity of REP-TILs and suggests that the addition of an anti-LAG-3 blocking antibody might be beneficial in these patients." (PMID 32547707, 2020). "However, according to the results of this study, if the ectopic expression of LAG‐3 in tumor cells can be confirmed, it may prove that LAG‐3 could have an anti‐tumor effect in addition to its role in immunological checkpoints." (PMID 32077528, 2020). "The expression of LAG3 and HAVCR2 also exhibited significant positive associations with intratumoral TILs, and immunofluorescence analysis confirmed the higher percentage of LAG-3+ and HAVCR2+ CD8+ T cells in the total CD8+ T cells in tumor epithelial nests compared with those in the tumor stroma." (PMID 32686767, 2020). "Similarly, LAG-3 could potentiate the sensibility of tumor cells to Tregs in case of a clinical relapse through mediating the inhibition of T lymphocytes." (PMID 33114418, 2020). "For these tumor groups, the therapeutic blockage of LAG3 could be considered as well." (PMID 32232506, 2020). "Thus, we assume that pro-inflammatory signalling pathways against the tumour could be compensatory regulation by the suppressive effect of LAG3." (PMID 32592066, 2020). "Given the functions of TIM-3 and LAG-3 in controlling T-cell activation, these molecules are under consideration as alternate pathways for the regulation of tumor-induced immune evasion that could be blocked to promote T-cell mediated anti-tumor immunity." (PMID 31007846, 2019). "Hence, we hypothesized that blocking LAG3 in addition to PD-1 blockade may increase tumor-specific T cell responses promoted by domatinostat." (PMID 31703604, 2019). "Some inhibitory receptors, such as PD-1, lymphocyte activation gene 3 (LAG-3), T cell immunoglobulin mucin 3 (TIM-3), cytotoxic T-lymphocyte-associated protein 4 (CTLA-4), are highly expressed on exhausted T cells during chronic viral infection and tumor progression." (PMID 31632413, 2019). "In tumor tissue, chronic exposure to antigen and the development of dysfunctional or exhausted effector T cell are accompanied by high expression of one or more inhibitory receptors including PD-1, lymphocyte activation gene 3 (LAG-3), and T-cell immunoglobulin and mucin-domain containing-3 (TIM-3)." (PMID 31639056, 2019). "Additionally, tumor-infiltrating CD4+ T cells upregulated programmed cell death protein-1 (PD-1), cytotoxic T-lymphocyte-associated protein-4 (CTLA-4), T cell immunoglobulin and mucin domain-3 (TIM-3) and lymphocyte-activation gene 3 (LAG-3)." (PMID 31921188, 2019). "Additionally, we believe that both increased lymphatics and their expression of PD-L1, along with increased PD-1 and Lag-3 expression by T cells in the tumor microenvironment could lead to increased tumor metastasis in tumors established during involution." (PMID 31244852, 2019). "Similarly, antibodies against PD-L1, TIM3, or LAG3 could restore responses of HCC-derived T cells to tumor antigens, and combinations of those antibodies had additive effects." (PMID 31708918, 2019). "The results from the various LAG3 clinical studies are currently unknown but the rationale behind them is based on data suggesting that co-targeting LAG3 is a promising approach for improving immunotherapy responses in multiple human tumor types." (PMID 31434339, 2019).
tumor (continued). "A hallmark of tumor-associated T cells is a state of hyporesponsiveness or functional exhaustion, marked by persistent expression of surface inhibitory markers including PD-1, CTLA4, LAG3, TIM3 and others, many of which are expressed following T cell activation." (PMID 31624246, 2019). "Those with a higher frequency of somatic mutations and tumor-specific neoantigens were found to have more abundant infiltration of CD8+ T lymphocytes and a higher expression of regulatory molecules (CTLA-4, PD-1, Lymphocyte-activation gene 3[LAG-3] and indolamine 2,3-dioxygenase 1 [IDO1])." (PMID 30104497, 2018). "Finally, we tested the hypothesis that the effect of LAG-3 blockade on proliferation of antigen-specific T cells can also be transferred to tumor antigen specificity." (PMID 29535740, 2018). "Hence, we next examined whether double blockade of PD-1 and LAG-3 could inhibit the tumor growth of KRS-SCCs, which would suggest a functional rescue of exhausted TILs." (PMID 27835902, 2016). "Blocking PD-1 and LAG-3 is particularly interesting because both are mainly expressed on TILs, which may result in a favorable safety profile due to restriction of T cell responses to the tumor-microenvironment." (PMID 27847783, 2016). "Preclinical data demonstrates that anti-LAG-3 is mildly effective as monotherapy, but potently synergizes with anti-PD-1, suggesting that the combined immune checkpoint inhibition could enhance T cell activity and improve anti-tumor immunity." (PMID 27912781, 2016). "More specific markers could be envisioned as predictive for benefit to anti-LAG-3, anti-Tim-3, or anti-4-1BB, for example, based on the presence of T cells in the tumor microenvironment that are dysfunctional, yet show surface expression of these receptors ex vivo." (PMID 24829752, 2013). "Tumor-infiltrating CD8+ T-cells also expressed significantly lower levels of exhaustion markers, including LAG-3, CTLA4 and TIM3." (PMID 41431358, 2026). "Further analyses showed that the combination treatment elevated PD-1, LAG3, TIM-3, and CTLA-4 expression in bulk tumor samples, a pattern most consistent with increased T-cell infiltration and activation." (PMID 41484455, 2026). "Immune checkpoint proteins including PD-1, CTLA-4, LAG-3, TIM-3, and TIGIT regulate T-cell functions, which are essential for anti-tumor immunity." (PMID 41681956, 2026). "Reduction in mean fluorescence intensities (MFI) of LAG3, TIGIT and TIM3 in CD8+ tumor infiltrating lymphocytes of dual PI3Kγ/PD-L1 treatment was observed." (PMID 41431358, 2026). "Recent findings have described CD19+ LAG-3+ B cells in murine 4T1 and EO771 models and human TNBC, which are enriched in tumor-draining LNs and display signatures of proliferation." (PMID 41364090, 2026). "LAG-3 inhibits T cell activation, cytokine production, and proliferation upon engagement with its canonical ligand MHC class II, thereby promoting tumor immune escape." (PMID 41486149, 2026). "Upon exposure to tumor cells, T cells from PWH showed significantly increased expression of exhaustion markers (LAG3, PD-1, TIM3, and CD39) but decreased expression of activation markers (CD25 and CD69) compared with T cells from PWOH." (PMID 40459946, 2025). "Although blockade of the checkpoint molecules LAG-3, PD1/PD-L1, and TIGIT aims to activate anti-tumor CD8+ cytotoxic T cells, they also reactivate and expand exhausted Tregs, contributing to therapy resistance." (PMID 40299510, 2025). "There was a significant correlation between high LAG3 expression and active CD4 + and CD8 + T cells in tumor cells." (PMID 40411616, 2025). "The groundbreaking evolution of tumor immunotherapy has unveiled novel immune checkpoint molecules, such as TIM3, LAG-3, and TIGIT, heralding new possibilities for cancer immunotherapy." (PMID 40362568, 2025). "The dual blockade of LAG-3 and PD-1 has shown synergistic effects in preclinical GBM models, leading to reduced tumor growth and prolonged survival." (PMID 40223940, 2025).
tumor (continued). "The expression of TIM-3, as well as PD-1, LAG3, and CTLA-4, are higher on T cells in HCC tumor tissue compared with normal liver tissue." (PMID 40076561, 2025). "We also clearly identified that high proportions of LAG3+, TIM3+, and CTLA4+ tumor-infiltrating iNKT cells were predictive of poor clinical outcomes." (PMID 41562072, 2025). "For the immune part, we focused on the TCR-mediated signaling pathway and major immune checkpoints including PD-1, PD-L1, CD28, CD80/CD86, LAG3, CTLA4, TIGIT, CD155, OX40, OX40L, 4-1BB, and 4-1BBL (expressed on T cells, tumor cells, or APCs)." (PMID 40276607, 2025). "Further research is required to explore the molecular mechanisms regulating B7-H3 and LAG3 expression on CD4 CTLs and to validate these findings in other tumor types." (PMID 40070836, 2025). "Our findings demonstrate that HLB-apt exerts dual antitumor effects likely through simultaneously targeting LAG3 on T cells and HER2 on tumor cells, facilitating T cell recruitment and potentially interfering with immune checkpoint pathways." (PMID 40761795, 2025). "A major challenge in CAR-T cell therapy for solid tumors is T cell exhaustion following tumor infiltration, characterized by upregulation of inhibitory receptors (e.g., PD-1, CTLA-4, LAG-3, TIM-3) and diminished proliferative capacity and antitumor activity." (PMID 40755764, 2025). "Overall, our results reveal a prevalence of NK and CD8+ T-cells with an increased expression of PD-1, TIM-3, LAG-3, and TIGIT on their surface in tumor-rich niches." (PMID 40227595, 2025). "These nominated clusters upregulated key marker genes of activation, dysfunction, and differentiation that have been used to identify tumor specificity, such as CXCL13, TIGIT, PDCD1 (PD1), ENTPD1 (CD39), TOX, HAVCR2 (TIM-3), and LAG3." (PMID 40848148, 2025). "Re-expression of alternative immune checkpoints, such as LAG-3, TIM-3, and TIGIT, contributes to tumor immune escape and resistance to PD-1/PD-L1 blockade." (PMID 40361336, 2025). "Cholesterol‐enriched tumor tissues and elevated cholesterol within tumor‐infiltrating CD8+ T cells are positively correlated with increased expression of immune checkpoint molecules such as PD‐1, 2B4, TIM‐3, and LAG‐3." (PMID 41085102, 2025). "Studies have suggested that compared to Tregs in peripheral blood, tumor-infiltrating Tregs exhibit more proliferative and immunosuppressive phenotypes, with increased expression of CTLA-4, CD25, GITR, 4−1BB, OX40, ICOS, LAG-3, TIM3, TIGIT, and PD-1." (PMID 40587482, 2025). "Upregulation of LAG-3, TIM-3, TIGIT, and VISTA has been observed in patients with tumor recurrence after anti-PD-1/L1 or anti-CTLA-4 therapy, indicating the presence of an underlying mechanism of acquired resistance." (PMID 40075727, 2025). "The present study uncovered a DCDC2/ENO1/FGL1/LAG-3 axis and communication between ICC tumor cells and CD8+ T cells." (PMID 40533767, 2025). "Our results show that strategically targeting TIM3, LAG3, TIGIT, CTLA4, IFITM, TREM2 and PD-1 in MMRd and also MMRp CRC tumors not only further limits tumor growth but can also significantly increase the complete elimination of tumors." (PMID 40027748, 2025). "Lymphocyte activation gene-3 (LAG-3) is a crucial immune checkpoint that modulates immune responses during infection and tumor." (PMID 41023624, 2025). "The MAOA gene is highly expressed in tumor-infiltrating, exhausted CD8 T-cells, especially those with elevated PD-1, Tim-3, and LAG-3 levels, making them less effective at fighting cancer." (PMID 40298832, 2025). "Blocking the LAG-3 pathway can activate antigen-specific T cells within the TME, restore their cytotoxic function, and inhibit tumor growth." (PMID 40796887, 2025). "Based upon our observations, we next investigated the impact of targeting T cell checkpoints on tumor growth by using anti-TIM3, anti-TIGIT, anti-LAG3, or anti-CTLA4, alone or in combination with anti-PD-1." (PMID 40027748, 2025).
tumor (continued). "Several transcripts associated with immunological checkpoints, such as SIGLEC15, PDCD1LG2 (PD-L2), TIGIT, PDCD1 (PD-1), CD274 (PD-L1), CTLA4, LAG3, and HAVCR2 (TIM3), play a crucial role in tumor immune evasion." (PMID 40893939, 2025). "Further studies on the role of immune checkpoints, including PD‐1/PD‐L1, TIM‐3, LAG‐3, and TIGIT, in the tumor microenvironment are needed to explore their potential as therapeutic targets." (PMID 40347011, 2025). "By combining anti-PD-1 with anti-LAG3/CTLA4/TREM2, up to 100% tumor eradication was achieved in MMRd CRC and remarkably, in >70% in MMRp CRC." (PMID 40027748, 2025). "Lymphocyte activation gene-3 (LAG3), an important suppressive immune checkpoint in tumor immunity, exhibits a wobbling effect in the prediction of ESCC efficacy." (PMID 40411616, 2025). "Immune checkpoint molecules, including PD1, LAG3, and CTLA4, are crucial to regulate the T cells function in the tumor microenvironment." (PMID 40481915, 2025). "Consistently, much lower levels of LAG3 and TIM3 were detected among the tumour‐infiltrating CAR‐T cells collected from portal vein injection tumours compared to those from tail vein injection." (PMID 41267637, 2025). "ICIs enhance anti-tumour immunity by targeting the inhibitory checkpoint receptors CTLA-4, PD-1, PD-L1, and LAG-3." (PMID 40265076, 2025). "This shift is evidenced by the upregulation of inhibitory receptors including PD-1, CTLA-4, LAG-3 and TIM-3, which results in T cell exhaustion and failure of their anti-tumour effector function." (PMID 39859271, 2025). "A bispecific peptide LFOP targeting PD-1/PD-L1 and LAG-3/FGL1 has the ability to activate T cells and increase tumor infiltration with T lymphocytes, and the effect is synergistic with irradiation, amplifying the immune response." (PMID 40277786, 2025). "Considering high expression of LAG3 on CD8+ T cells, we first assessed the impact of lead-in therapy on tumor immune microenvironment changes of CD8+ T cells in relation to other immune subtypes, using a custom multiplex immunofluorescence panel." (PMID 41282765, 2025). "PSMB9 displayed strong correlations with classical inhibitory molecules such as LAG3, PDCD1, CTLA4, TIGIT, HAVCR2, SLAMF7, and PD-L1 across nearly all tumor types." (PMID 41020834, 2025). "Humanised monoclonal antibody ICIs, including PD-1, CTLA-4, LAG-3 and TIM-3, target T cell immunoregulatory receptors utilised by tumours to suppress the immune response, promoting T cell mediated tumour recognition, cytotoxicity and death." (PMID 39859271, 2025). "MPE T cells exhibited lower levels of co-inhibitory receptors (PD-1, LAG-3, TIGIT, TIM-3) expression relative to tumor." (PMID 41415427, 2025). "They suppress anti-tumor immune responses through secretion of IL-10, IL-35, and TGF-β, and via expression of immune checkpoint molecules such as CTLA-4 and LAG-3." (PMID 41244711, 2025). "Numerous transcripts related to immunological checkpoints, including SIGLEC15, PDCD1LG2 (PD-L2), TIGIT, PDCD1 (PD-1), CD274 (PD-L1), CTLA4, LAG3, and HAVCR2 (TIM3), are integral to tumor immune evasion mechanisms." (PMID 41194934, 2025). "We also investigated the impact of targeting myeloid cell checkpoints together with T cell checkpoints on tumor growth by using anti-IL1B, anti-TREM2 or anti-IFITM, alone or in combination with anti-PD-1/CTLA4/LAG3." (PMID 40027748, 2025). "In the atlas, we detected LAG3 expression in several cell groups, including Treg cells, CD8+ T cells, neutrophils, and tumor cells." (PMID 41025546, 2025). "In line with the observations in mice, the proportions of PD-1+, GITR+ and LAG-3+ cells increased among CD4+ and CD8+ T cells in the tumor compared to the blood." (PMID 39751916, 2025). "They showed that the dMMR subset of tumours selectively upregulated multiple checkpoint proteins, including PD-L1, PD-1, CTLA-4, IDO, and LAG3." (PMID 40647497, 2025).
tumor (continued). "RT is characterized by profound alterations in immune checkpoint molecules, including Programmed Death-1 (PD-1), Lymphocyte Activation Gene-3 (LAG3), and T-cell Immunoreceptor with Ig and ITIM domains (TIGIT), which collectively impair anti-tumor immunity." (PMID 40565027, 2025). "This signature includes key genes for maintaining cellular cytotoxicity such as ZNF683,41PRF1, IL2RB, and IFNG and immune activation and exhaustion markers including LAG3, PDCD1, PRF1, and TBX21 that contribute to anti-tumor immunity." (PMID 41045934, 2025). "The fluorescence intensity of tumor tissue in HLB-apt and HER2-apt treatment groups was significantly higher than that in LAG3-apt and PBS treatment groups (P<0.001)." (PMID 40761795, 2025). "Clinical trials exploring combination checkpoint blockade, such as LAG-3 and TIM-3 co-inhibition along with PD-1 blockade, are ongoing to enhance anti-tumor efficacy while managing toxicity." (PMID 41268982, 2025). "Immune checkpoints such as PD-1/PD-L1, CTLA-4, LAG-3, TIM-3, and TIGIT play critical roles in regulating anti-tumor immunity and are exploited by hematological malignancies to evade immune surveillance." (PMID 40723175, 2025). "This unique tumor cluster exhibited high gene expression of 22 genes, including immune checkpoint regulators, like CTLA4, TIGIT, LAG3, and CD27, immune cell surface markers, and inflammatory genes." (PMID 40492347, 2025). "The high expression of inhibitory receptors such as LAG3,KLRG1, and TIM3 implies that the abnormal expression of these molecules is closely related to T-cell functional failure and the weakening of anti-tumor immune responses." (PMID 41394809, 2025). "In MMRd tumors, resistance following anti-PD-1 treatment is driven by the expression of TIM3, LAG3, CTLA4, and TIGIT by TILs, as well as tumor clonal selection and the expression of TREM2, CSF1R, IFITM, TMEM176B and IL1B by myeloid cells." (PMID 40027748, 2025). "In the tumor microenvironment (TME), exhausted CD8+ T cells (Tex) simultaneously overexpress PD-1, TIM-3, LAG-3, and TIGIT." (PMID 40821806, 2025). "Additional interactions with CTLA4, LAG3, LGALS9, and CD4 placed PD-1 at the center of a dynamic immunoregulatory network critical for tumor immune evasion." (PMID 40927719, 2025). "Immune checkpoints like PD-1/PD-L1, TIM-3, LAG-3, and CTLA-4 are critical in tumor immune evasion, as they inhibit T-cell activation, enabling tumors to bypass immune surveillance." (PMID 40870970, 2025). "In T cells, downregulation of AL031775.1 impairs antitumor immunity, upregulates immune checkpoint molecules LAG3, PD1, and CTLA4, and diminishes T-cell cytotoxic activity against tumor cells." (PMID 40066455, 2025). "In a limited cohort of 10 patients treated with relma-cel, the CR group demonstrated significantly higher relative mRNA expression of LAG3 and CTLA4 in pre-treatment tumor biopsies." (PMID 39858099, 2025). "A significantly elevated expression of checkpoint inhibitors was detected in Cluster two tumours, including PD-1, PD-L1, CTLA4, CD80/CD86 costimulatory molecules, and emerging targets like TIGIT and LAG3." (PMID 41050056, 2025). "Most importantly, the prolonged inflammation and high tumour burden of CLL lowers CD16 expression, while also upregulating that of LAG-3." (PMID 40136700, 2025). "When the tumor volume of the mice reached about 50 mm3, PBS, Jurkat cells, LAG3-apt + Jurkat cells, HER2-apt + Jurkat cells, and HLB-apt + Jurkat cells were used for treatment, and the mice were euthanized 36 days later." (PMID 40761795, 2025). "GITR agonists have demonstrated synergy with PD-1 and LAG-3 inhibitors in murine models of melanoma and NSCLC, leading to improved tumor control and survival." (PMID 40777027, 2025). "Recent studies have highlighted the inhibitory effects of high LAG‐3 and PD‐1 expression on CD8+ T cells, reducing their tumor‐killing ability." (PMID 40091778, 2025).